METTL14 (methyltransferase 14, N6-adenosine-methyltransferase non-catalytic subunit)
Diseases named in the same sentence as METTL14 in open-access papers (continued):
Sharing a sentence is not in itself a finding about the gene and the disease.
glioblastoma (40 papers, 2017 to 2025). The most malignant astrocytic tumor (WHO grade IV). "METTL14 deficiency considerably accelerates the propagation, self‐renewal, and oncogenesis of glioblastoma stem cells (GSCs)." (PMID 34904301, 2022). "In glioblastoma, inhibition of METTL3 and METTL14 expression promotes the development of glioblastoma, and up-regulation of METTL3 or inhibition of FTO expression through MA2 delays tumor growth." (PMID 39033180, 2024). "Decreased methyltransferases METTL14 can promote the malignant attribute of glioblastoma stem cells while suppressing the demethylase FTO plays the opposite role." (PMID 36105083, 2022). "Despite the unanimously oncogenic functions of METTL3 and METTL14 in all these cancer types, in glioblastoma and HCC several reports have demonstrated both, oncogenic and tumour suppressive roles." (PMID 33461542, 2021). "METTL14 knockdown had a positive impact on glioblastoma stem cell growth by decreasing the expression of ADAM19 in an m6A-dependent manner." (PMID 34699322, 2021). "METTL3 and METTL14 are essential m6A methyltransferases and have been reported to be involved in tumorigenesis of glioblastoma stem cells." (PMID 34863175, 2021). "Downregulation of METTL3 or METTL14 can promote proliferation and self-renewal of glioblastoma stem cells by reducing the m6A level on ADAM19 mRNA, which enhances its stability and finally promotes the occurrence of glioblastoma." (PMID 34900689, 2021). "The low expression of m6A regulators METTL14 in HCC and the overexpression of the m6A regulator ALKBH5 in glioblastoma have been both associated with poor prognosis." (PMID 33643384, 2021). "Intriguingly, reasons of m6A dysregulation in CSCs are different among various types of cancer, considering the roles of FTO, ALKBH5, and METTL3 in glioblastoma stem cells and of METTL14 and FTO in leukemia stem cells." (PMID 32676121, 2020). "In glioblastoma tumor, the key m6A writers known to have a potential role in tumor course are METTL14 and METTL3, for which the experimental knocking-down expression in cellular models results in tumor cell growth." (PMID 30654440, 2019). "METTL3 or METTL14 knockdown dramatically promotes human glioblastoma stem cell growth, self‐renewal and tumorigenesis." (PMID 29502358, 2018). "Low levels of METTL3 or METTL14, key components of the RNA methyltransferase complex, have been shown to reduce the expression of m6A-modified ADAM19 RNA, whereas high ADAM19 RNA expression in glioblastoma stem cells causes glioblastoma." (PMID 34136491, 2021). "For instance, the increased expression of METTL3 and METTL14 in brain and CNS cancer might explain their promotion role in growth and tumorigenesis of glioblastoma stem cells." (PMID 30953473, 2019). "In glioblastoma (GBM), METTL14 is highly expressed and enhances PD-L1 stability by promoting its m6A modification." (PMID 41164187, 2025). "In glioblastoma, we observed that both METTL3 and METTL14 are highly expressed compared to normal brain; additionally, we found that the A-to-I overall editing is decreased in GBM, despite the high levels of ADAR1 protein found in this type of tumor." (PMID 33509238, 2021). "Conversely, some m6A genes have been found to act as tumor suppressor genes or oncogenes, for example, METTL3 and METTL14, in neurological tumors such as glioblastoma (GBM)." (PMID 33519919, 2020). "In glioblastoma, the overexpression of m6A methyltransferase METTL3 or METTL14, or correspondingly, the knockdown of FTO inhibited the growth and self-renewal of glioblastoma stem cells." (PMID 39198433, 2024). "In cases of glioblastoma (GBM), HCC, and CRC, METTL14 is identified as a tumor suppressor and downregulated." (PMID 36226062, 2022).
glioblastoma (continued). "Dysregulation of m6A “writer” protein, methyltransferase-like 3 (METTL3) and methyltransferase-like 14 (METTL14), has been reported in liver cancer, lung cancer and glioblastoma." (PMID 32111213, 2020). "For human glioblastoma U251 cells and human colon cancer HCT116 cells, the results strongly supported that the m6A writers METTL3 and METTL14 were down‐regulated upon the addition of bile acids, especially at high concentrations." (PMID 38713722, 2024). "This study revealed the biological significance of m6A modification in glioblastoma biology, defining the role of m6A modification in GSC self-renewal and tumorigenesis by targeting multiple components of the m6A regulatory machinery, including METTL3, METTL14, and FTO." (PMID 28297667, 2017). "A similar finding is indicated for glioblastoma stem cells, METTL14 knockdown could enhance glioblastoma stem cell growth, self-renewal and tumorigenesis by enhancing m6A modification of ADAM19 and decreasing its expression, suggesting a tumor suppressor role of METTL14." (PMID 33430867, 2021).
leukemia (36 papers, 2018 to 2026). A malignant (clonal) hematologic disorder, involving hematopoietic stem cells and characterized by the presence of primitive or atypical myeloid or lymphoid cells in the bone marrow and the blood. "Highly selective inhibition of the METTL3/METTL14 complex and demonstration of anti-leukemia activity in AML cell lines including MOLM-13, MOLM-14, HL60, etc." (PMID 41157107, 2025). "In leukemia, METTL14, which is negatively regulated by SPI1, exerts its oncogenic effects by regulating m6A modification of its mRNA targets (e.g., MYB and MYC)." (PMID 37932821, 2023). "For example, the methyltransferase METTL-14 promotes the occurrence and development of leukemia via m6A RNA modification of MYB/myc." (PMID 37529797, 2022). "METTL14 has also been reported in leukemia; METTL14 exerts oncogenic effects by regulating its mRNAs (MYB and MYC) through m6A modifications." (PMID 35487915, 2022). "METTL14 is required for the development and self-renewal of leukemia stem/initiating cells by regulating the expression of genes such as MYB and MYC21." (PMID 35154467, 2022). "A study on leukemia also found that METTL14 can block myeloid differentiation and promote the self-renewal of normal HSPCs and LSCs/LICs (leukemia stem cells/leukemia-induced cells)." (PMID 33628845, 2021). "METTL14 inhibited hematopoietic stem cell/progenitor cell differentiation and promotes leukemia by enhancing the m6A modification of MYB (HGNC:7545)/MYC (HGNC:7553)." (PMID 35087827, 2021). "In contrast to increased m6A/METTL3 in most tumor types, decreased METTL14/m6A has been reported to act as a tumor suppressor, and elevated METTL14 expression has been reported in a variety of solid tumors and leukemia through various mechanisms." (PMID 33922187, 2021). "There are few pieces of researches focused on mutations in m6A-related genes in prostate cancer, but in AML, mutations in m6A writers such as METTL3, METTL14 and WTAP can enhance progression of leukemia, conferring unfavorable survival outcomes." (PMID 32710725, 2020). "Furthermore, we found that the autophagy inhibition through knockout of ATG5 in KrasG12D/+ mutant mice promoted the expansion of HSPCs and inhibited the progression of leukemia disease, consistent with the phenotypes of knockout of METTL14." (PMID 40819104, 2026). "Consequently, our results suggest that the knockout of METTL14 can promote the expansion of HSPCs and inhibit the disease process of leukemia by inhibiting HSPCs autophagy." (PMID 40819104, 2026). "For example, m6A mediated by METTL3 and METTL14 methyltransferase complex is an abundant RNA modification on mammalian mRNA, which plays important roles in hematopoietic development and the maintenance of hematopoietic and leukemia stem cells." (PMID 40382345, 2025). "METTL14 causes the occurrence and development of leukemia by modifying MYB/MYC-targeted genes with m6A RNA, and m6A promotes the translation of c-MYC, BCL2, and PTEN in leukemia patients." (PMID 38970366, 2024). "For example, in leukemia, METTL14 was shown to promote stemness by inducing MYC and MYB expression." (PMID 39563370, 2024). "STM2457, a compound that reduces m6A modification by suppressing the METTL3/METTL14 complex, has shown good antitumor effects in malignant tumors including leukemia, cholangiocarcinoma, and osteosarcoma and has shown potential in reversing liver and lung cancer resistance." (PMID 39268503, 2024). "Next, the expression of METTL3 and METTL14 in leukemia cell lines was examined." (PMID 35154467, 2022).
leukemia (continued). "In addition, METTL14 knockdown promotes myeloid differentiation, inhibits cell growth, induces apoptosis in vitro, significantly delays leukemia onset, and prolongs survival in immunodeficient recipient mice in vivo." (PMID 34001273, 2021). "However, another research demonstrated that METTL14 functioned as an oncogene to promote tumorigenesis by mRNA m6A modification in leukemia." (PMID 32038982, 2020). "In addition, the ablation of METTL14 delayed the onset of leukemia and prolonged the survival of mice." (PMID 31024852, 2019). "However, in transplantation experiments, mouse HSCs deleted for METTL3 or METTL14 showed reduced repopulation ability and the deletion of METTL14 from primary leukaemia blasts significantly delayed leukaemia onset in recipient mice." (PMID 30096915, 2018). "Thus we speculate that the downexpression of METTL3 and METTL14 contributes to not only the development of leukemia but also to relapse." (PMID 31429529, 2019). "In leukemia cell lines, knockdown of METTL3 or METTL14 inhibited cell proliferation, induced cell cycle arrest and decreased the ability of the cells to form colonies." (PMID 35154467, 2022). "METTL14 is required for both the initiation and maintenance of AML and the self-renewal of leukemia stem/initiation cells." (PMID 35538475, 2022). "In leukemia cell lines K562 and kasumi-1, both METTL3 and METTL14 promote cell proliferation and cell cycle, and the knockdown of METTL3 and METTL14 inhibits proliferation, and induces apoptosis and differentiation." (PMID 35154467, 2022). "In SPI1-METTL14-MYB/MYC axis, METTL14, is downregulated by SPI1, exerts an oncogenic role in enhancing leukemia stem/initiating cells self-renewal and repressing myeloid differentiation by regulating MYB and MYC via m6A modification." (PMID 30062093, 2018). "More importantly, the METTL3/METTL14 methylation complex was found to promote the development of AML and maintain leukaemia-initiating cells in transplantation mouse models." (PMID 30096915, 2018). "Interestingly, a genome-wide CRISPR/Cas9 screening performed in mouse primary leukemia cells expressing both FLT3-ITD and MLL-AF9 fusion genes identified besides METTL3 and METTL14 also METTL16 as critical gene for AML survival." (PMID 31024852, 2019). "So we speculated that the downexpression of METTL3 and METTL14 in E/R‐positive ALL may affect the m6A modification of some genes in leukemic cells, and then promote the development of leukemia." (PMID 31429529, 2019). "Especially, METTL3 and METTL14 are also involved in various aspects of the occurrence and development of AML dependent or independent on their m6A methyltransferase activity, including maintenance of the leukemic state, therapeutic resistance, and leukemia cell survival and differentiation." (PMID 40382345, 2025). "Additionally, FTO can enhance the stability of MYC and CEBPA mRNA, thereby promoting cell proliferation, and METTL14 and YTHDF2 promote the self-renewal of leukaemia stem cells (LSCs)/leukaemia initiating cells (LICs), while ALKBH5K promotes LSC proliferation and induces apoptosis." (PMID 39641872, 2024). "Furthermore, METTL14 is highly expressed in acute myelocytic leukaemia (AML) and can promote the occurrence of AML by inhibiting the degradation of MYB and MYC mRNA, promoting its translation and maintaining the self-renewal of leukaemia stem cells." (PMID 34900689, 2021). "Here, we have described how RNA m6A-modification machineries EEE (Editor/writer: Mettl3, Mettl14; Eraser/remover: FTO, ALKBH5, and Effector/reader: YTHDF-1/2) could be reformed into potential druggable candidates or as RNA-modifying drugs (RMD) to treat leukaemia." (PMID 34207299, 2021).
bladder cancer (33 papers, 2019 to 2025). "Low expression of METTL14 and decreased global m6A abundance in bladder cancer tissue are also associated with the clinical severity and outcomes of bladder cancer." (PMID 35004679, 2021). "METTL14 expression is negatively associated with the severity of bladder cancer and clinical outcome." (PMID 32765970, 2020). "For example, in bladder cancer, METTL14 is upregulated, leading to the promotion of lncDBET expression through METTL14-mediated m6A modification." (PMID 40271153, 2025). "In contrast, another study on bladder cancer shows that METTL14 is downregulated in bladder tumor-initiating cells (TICs), and its deletion increases TIC self-renewal and bladder tumorigenesis." (PMID 40271153, 2025). "The positive feedback loop mediated by USP38 effectively inhibits the malignant progression of bladder cancer, underscoring its important role in the regulatory mechanism of METTL14." (PMID 40936898, 2025). "For instance, miR-3165 suppresses METTL14 expression in bladder cancer, promoting tumor progression via the miR-3165–METTL14–USP38 axis." (PMID 41164187, 2025). "In bladder cancer, METTL14 suppressed the development and progression of cancer cells by regulating Notch1." (PMID 39054337, 2024). "METTL14 represses bladder cancer cell migration, invasion, and EMT by increasing the expression of USP38." (PMID 36835633, 2023). "USP38 mediates METTL14 protein deubiquitination; therefore, METTL14 overexpression inhibits bladder cancer cell (BCa) malignancy." (PMID 37391814, 2023). "Nevertheless, METTL14 has been confirmed to be decreased in bladder cancer, and depletion of Mettl14 accelerated cell proliferation, tumour metastasis and self-renewal by decreasing the stability of m6A-modified Notch1 transcripts." (PMID 36407103, 2022). "The expression level of METTL14 of bladder cancer and tumor-initiating cells showed a decrease, and it was significantly related to the clinical severity and prognosis of bladder cancer." (PMID 34604051, 2021). "METTL14 is expressed at low levels in kidney and bladder cancer, where it has a tumor suppressive role." (PMID 32765970, 2020). "METTL14 gene knockout promotes the proliferation, metastasis, and tumor initiation capacity of bladder cancer cell lines (TICs), this phenomenon disappears once METTL14 is overexpressed." (PMID 33552994, 2020). "Among these genes, Mettl14 was lowly expressed in bladder cancer, especially in advanced bladder cancer samples." (PMID 31760940, 2019). "driverMAPS identified the genes METTL3 and METTL14 as driver genes in the cohorts BLCA (bladder cancer) and UCEC (uterine cancer), respectively." (PMID 31363082, 2019). "m6A level and Mettl14 expression were negatively related to the bladder cancer severity and clinical outcome." (PMID 31760940, 2019). "Altogether, Mettl14 was lowly expressed in bladder cancer and accounted for the decreased content of m6A modification." (PMID 31760940, 2019). "Interestingly, METTL14 is expressed at low levels in bladder cancer, and METTL14 knockout can promote proliferation, self-renewal, metastasis and tumor-initiating capacity." (PMID 40986143, 2025). "There has been some research on the function of METTL3 and METTL14 in bladder cancer." (PMID 40133252, 2025). "METTL14 also inhibits the proliferation of bladder cancer cells." (PMID 39289775, 2024). "miR-3165 promoted bladder cancer (BCa) progression by targeting METTL14 expression." (PMID 36835633, 2023). "METTL14 is downregulated in kidney and bladder cancers, playing a tumour suppressive role." (PMID 35004679, 2021). "We found that a low expression of METTL14 (a m6A methyltransferase), SMPD4, and SGK2, but a high expression of ALKBH5 (a m6A de methyltransferase), LINC00482, and HIPK3, showed a tendency to associate with worse overall survival in bladder cancer patients." (PMID 34868913, 2021).
bladder cancer (continued). "In addition, METTL14 expression is downregulated in bladder cancer, and some studies have shown that eliminating METTL14 promotes capsule proliferation." (PMID 34660577, 2021). "METTL14 is expressed at low levels in bladder cancer and bladder tumor-initiating cells (TICs)." (PMID 32765970, 2020). "METTL14 is expressed at low levels in kidney and bladder cancer playing tumor suppressive role." (PMID 32765970, 2020). "The essential role of Notch1 in Mettl14 function was confirmed in T24 bladder cancer cell line." (PMID 31760940, 2019). "Mettl14 is lowly expressed in bladder cancer and bladder TICs." (PMID 31760940, 2019). "Additionally, miR-3165 can inhibit METTL14 expression to promote bladder cancer progression." (PMID 40986143, 2025). "In addition, studies in bladder cancer demonstrate that specific circRNAs can scaffold the WTAP/METTL3/METTL14 complex to remodel m6A on target mRNAs and thereby modulate chemosensitivity, highlighting the potential bidirectional interplay between circRNAs and the m6A machinery in cancer." (PMID 41323393, 2025). "Another research manifested that the m6A levels of total RNA were increased, and METTL14 was the main m6A-related enzyme in the bladder cancer (BC); as well as METTL14-mediated m6A modification could promote malignant progression of BC through up-regulating lncDBET expression." (PMID 38326804, 2024). "Thus, METTL14 is a tumor suppressor in bladder cancer, acting through the METTL14-Notch1 pathway." (PMID 32765970, 2020). "Moreover, targeting both USP38 and METTL14 in therapy could theoretically enhance the inhibition of bladder cancer tumor cells, offering new insights and recommendations for targeted treatment of bladder cancer." (PMID 40936898, 2025). "In bladder cancer, METTL14 induces lncDBET overexpression, and along with FA binding protein 5 (FABP5), it promotes lipid metabolism and the malignant progression of bladder cancer." (PMID 38721006, 2024). "Most of the available research on methyltransferases in bladder cancer suggests that METTL3 is a oncogene, whereas METTL14 is a tumor suppressor." (PMID 32765970, 2020). "The reciprocal regulatory circuit between METTL14 and USP38 can promote EMT in bladder cancer." (PMID 40986143, 2025). "METTL14, YTHDC1, and WTAP may be protective factors for bladder cancer, the higher expressions were related to the longer overall survival of patients, while IGF2BP1-3, YTHDF1, LRPPRC, ALKBH5, and FTO were risk factors for bladder cancer." (PMID 37701836, 2023).